WNT5A (Wnt family member 5A)
Diseases named in the same sentence as WNT5A in open-access papers (continued):
Sharing a sentence is not in itself a finding about the gene and the disease.
lung cancer (continued). "Targeting of CCNB1 by miR-548b and Wnt5a by miR-374a have also been reported in lung cancer cell lines, with both serving as tumor repressors." (PMID 32316322, 2020). "The functional experiment of this part revealed that Wnt5a declined in lung cancer cells introduced with miR-326, and its expression was increased with miR-326 inhibitor, suggesting Wnt5a was negatively regulated by miR-326 in lung cancer." (PMID 33987473, 2020). "Wnt5a, an essential component of this pathway, increases the resistance of lung cancer cells to Cis-Pt through the activation of the Wnt5a/PKC signaling pathway." (PMID 31671889, 2019). "Increased signaling due to upregulation of Wnt ligands, specifically Wnt5a, contributes to poor clinical outcome and increased drug resistance, e.g., in ovarian carcinoma and lung cancer." (PMID 31671889, 2019). "In fact, an accumulation of several Wnt participants, including WNT1, WNT2, WNT3, WNT5a, FZD8, Dsh, Porcupine, and TCF4, has been reported in patients with lung cancer, and this accumulation is associated with a poor prognosis." (PMID 31608072, 2019). "Increased signaling due to upregulation of Wnt ligands, specifically Wnt5a, contributes to poor clinical outcome and increased drug resistance, e.g., in ovarian carcinoma and lung cancer, and also in MM cells." (PMID 31671889, 2019). "First, to the best of our knowledge, this is the first report showing that miR-1253 is down-regulated in NSCLC and that it is inversely correlated with the expression of WNT5A (long isoform), a novel target in lung cancer." (PMID 29415994, 2018). "In the case of lung cancer, Wnt5a exhibited an ability to promote cell migration and invasion in vitro and metastasis in vivo, which was significantly associated with malignant features of many cancer types." (PMID 27895670, 2016). "Several studies have demonstrated that Wnt5a is upregulated in lung cancer, especially in squamous cell carcinoma, and overexpression of Wnt5a is associated with poor prognosis in NSCLC patients." (PMID 26305508, 2015). "WNT5A was found to be overexpressed in many solid tumors, such as in breast, prostate, colon, and lung cancers." (PMID 26316480, 2015). "Knockdown of Wnt5a indeed suppressed proliferation of HeLaS3 cervical cancer cells as well as A549 and Calu-6 lung cancer cells." (PMID 25622531, 2015). "Although Wnt5a was considered as an oncogene in lung cancer, its role in angiogenesis of lung cancer is still ambiguous." (PMID 24999479, 2014). "In a recent report was shown that the Wnt5a gene is overexpressed in lung cancer, especially in squamous cell carcinoma, and that this overexpression is associated with a poor prognosis in NSCLC patients." (PMID 23349696, 2013). "In conclusion, these results suggest that cigarette smoke induces Wnt5a-coupled PKC activity during lung carcinogenesis, which causes Akt activity and anti-apoptosis in lung cancer." (PMID 23349696, 2013). "Next, we performed quantitative PCR on three Wnt pathway genes (FZD6, DVL3, WNT5A) in a commercial panel of 40 lung cancer samples (Origene; Rockville, MD)." (PMID 22016777, 2011). "CSC-exposure as well as Dkk-1 knock-down enhances Wnt-5a expression, and significantly increases proliferation and tumorigenicity of lung cancer cells." (PMID 21048943, 2010). "In our experimental setting, transcription of WNT-5A was down-regulated in stage 2 NSCLC, thus underlying a putative tumour suppressor function of its gene product in lung cancer progression." (PMID 18793406, 2008). "Overexpression of WNT5A up-regulation has been observed in various cancers, including lung cancer." (PMID 40282506, 2025). "Wnt5a-related mechanisms in regulating cancer cell behavior and their effects on inflammatory processes make Wnt5a a candidate for shared molecular pathways between lung cancer and RA." (PMID 40282506, 2025).
lung cancer (continued). "Given the involvement of WNT-5A in non-canonical WNT signaling and its association with conditions such as asthma, lung cancer, and COPD, it is plausible that WNT-5A might influence β-catenin activity indirectly." (PMID 39337534, 2024). "Finally, the ability of JPX to inhibit the silencing activity of miR-378a-3p toward its targets GLUT1, NRP1, YY1, and Wnt5a, and thus the contribution to lung cancer, was demonstrated." (PMID 38672608, 2024). "It has also been reported that Wnt5a is highly expressed in metastatic lung cancer cells." (PMID 37703992, 2023). "A recent study has found that cigarette smoke extract could inhibit the expression of GPRC5A in normal human lung epithelial cells and lung cancer cells, inducing the expression of WNT5a and the pathogenesis of lung cancer." (PMID 37486552, 2023). "Interestingly, Wnt5A gene expression has been found to be significantly positively correlated with overall survival in lung cancer patients." (PMID 37047688, 2023). "In a recent study, IL-37 inhibits tumor growth by regulating RNA m6A methylation in lung cancer cells, may downregulate the proliferation by inhibiting Wnt5a/5b pathway in lung cancer cells." (PMID 34248996, 2021). "In lung cancer, proliferation was positively correlated with WNT5A expression." (PMID 33639039, 2021). "Thus, we investigated the role of miR-326 on lung cancer cells in vitro, research results indicated that Wnt5a was directly targeted by miR-326 and a significant inverse correlation between them was also confirmed." (PMID 33987473, 2020). "Moreover, overexpression of Wnt5a overturned the effects on viability, proliferation, invasion, apoptosis, and Wnt/β-catenin restraint of miR-326 expression in lung cancer cells." (PMID 33987473, 2020). "Some genes such as MMP11 (extra-cellular matrix proteins), XRCC1 (DNA repair), VEGF (regulator of angiogenesis), Cyclin D1 (cell cycle regulators) and tumor-suppressor genes (Semaphorin 3B, WNT-5A) have been found as down-regulated genes during lung cancer progression." (PMID 29593668, 2018). "Consistently with previous findings, we also demonstrated that Wnt5a could enhance the mobility and stemness of lung cancer cells, including migration, invasion, colony formation, and chemoresistance, through a Wnt/PKC pathway." (PMID 27895670, 2016). "The results demonstrated that Wnt5a could enhance the capacity of proliferation, migration, invasion, and colony formation but reduce cell apoptosis in lung cancer cells, through activation of Wnt/calcium/PKC signaling pathway." (PMID 27895670, 2016). "In order to explore whether the Wnt5a-activated Wnt/PKC signaling has an effect on the characteristics of lung cancer cells, the colony forming capacity of A549 and A549/DDP cells was evaluated in terms of a clonogenic assay." (PMID 27895670, 2016). "Importantly, an inhibition of Wnt5a/calcium/PKC pathway by PKC inhibitor showed an increased cell apoptosis in cisplatin-resistant lung cancer A549/DDP cells." (PMID 27895670, 2016). "Owing to Wnt5a being implicated in chemoresistance of several epithelial cancer cells, we next sought to investigate the influence of Wnt5a/PKC signaling in cell apoptosis and cisplatin-resistance in lung cancer cells." (PMID 27895670, 2016). "Of interest, an inhibition of PKC signaling by GF109203X led to a significantly reduced ALDH-positive fraction in A549-DDP cells (p < 0.05), implying that Wnt5a/PKC signaling may be involved in the stemness of lung cancer stem cells." (PMID 27895670, 2016). "However, the potential role of Wnt5a during pre-malignant transformation in lung cancer remains controversial." (PMID 23349696, 2013). "Nonetheless, Wnt5a seems to act as crucial as an oncogene in lung cancer." (PMID 23349696, 2013).
lung cancer (continued). "To determine whether the activations of Wnt5a-mediated PKC and Akt signaling are responsible for abnormal cell proliferation, we used CSC-transformed 1198 cells, which expressed high levels of Wnt5a, representing the earliest stage of lung cancer." (PMID 23349696, 2013). "Likewise, an up-regulation of Wnt5a was observed in lung carcinoma and discussed in connection with tumor progression." (PMID 19812696, 2009). "Therefore, we hypothesized that the HOXA11 gene could be regulated by the formation of a loop between Wnt5a and Wnt7a in human lung cancer." (PMID 28380439, 2017). "Immunoblotting assay further identified that the Wnt5a-inhibited apoptosis and GF109203X-mediated increase of apoptosis were associated with a decreased and an increased expression of proapoptotic proteins of Bax, caspase 3, and apoptosis inducing factor (AIF) in lung cancer cells, respectively." (PMID 27895670, 2016). "To investigate whether Wnt5a has a potential role during the early stage of lung cancer development by cigarette smoking, we first profiled Wnt5a mRNA and protein expressions in five HBE cells (NHBE, BEAS-2B, 1179, 1198 and 1170I) at different malignant stages established by exposing them to CSC." (PMID 23349696, 2013). "However, it remains unclear whether Wnt5a contributes to the development of smoking-related lung cancer." (PMID 23349696, 2013). "The results of qRT-PCR and WB assay showed that the expressions of Wnt5a and other proteins in the ATF-2 knockdown lung cancer cells (represented by si-ATF-2) were lower than those in the normal lung cancer cells." (PMID 35692887, 2022). "One in vitro study demonstrated that a protein kinase c (PKC) inhibitor, GF109203X, inhibits WNT5A-induced cell migration, invasion, and clonogenicity in A549 and A549/DDP (diammine dichloro platinum) lung cancer cells." (PMID 36230484, 2022). "Wnt5a also activates the Wnt5a/protein kinase C (PKC) signaling pathway, which promotes lung cancer stem cell characteristics and resistance to cisplatin." (PMID 35412951, 2022). "A previous study showed that Wnt5a/PKC signaling can increase the capacity of proliferation, migration, invasion, and colony formation but reduce cell apoptosis in lung cancer cells." (PMID 34326694, 2021). "miR-487b and miR-203 have been noted to work as tumor suppressive miRNAs in lung cancer by targeting KRAS, WNT5A, SUZ12, MYC, and BMI1 (miR-487b) and FZD2 (miR-203)." (PMID 32316322, 2020). "Evidence has accumulated that both WNT-5A and WNT-5B are involved in the development and progression of chronic lung diseases, including asthma, IPF, lung cancer, and COPD." (PMID 31557955, 2019). "In the lung, Wnt5a was found to correlate with cigarette smoke-related lung carcinogenesis by a mechanism of activating PKC/Akt pathway, by which Wnt5a inhibited lung cancer cell apoptosis." (PMID 27895670, 2016). "Abnormally increased Wnt5a expression was detected in pre-malignant and malignant HBE cells, and in the tumor tissues of lung cancer patients with a smoking history, which demonstrated a relationship between Wnt5a signaling and smoking." (PMID 23349696, 2013). "In lung cancer, SOX4 expression is probably related to the overregulation of WNT5A; then, SOX4, FOXM1, TCF3, and JUP might form a stable protein complex with other factors and co-factors for the regulation of transcriptional targets." (PMID 39228892, 2024). "This signifies the role of WNT5A in promoting lung cancer cell movement through WNT/PKC non-canonical pathway activation." (PMID 36230484, 2022). "We found that Wnt5a expression was increased in smoking-related pre-malignant transformed HBE cells and clinical tissue samples, and PKC was involved in Wnt5a-mediated early development of lung cancer." (PMID 23349696, 2013).
lung cancer (continued). "In the present study, we observed that ART, DHA, and ARTS inhibited the expression level of Wnt5-a/b, down-regulated those of LRP6 and Dvl2, and subsequently reduced those of downstream genes mediated by β-catenin (i.e., nanog, sox2, oct3/4, and cyclin D1) in two lung cancer cell lines." (PMID 27119499, 2016). "Importantly, the PKC inhibitor GF109203X could reduce the fraction of ALDH-positive lung cancer stem cells in A549/DPP cells and reverse the Wnt5a-inhibited cell apoptosis in A549 cells." (PMID 27895670, 2016). "The immunoblotting analysis revealed that Wnt5a could increase the expression of phosphorylated PCK (phos-PKC), CaMKII, and NFκB in the Wnt/PKC signaling cascade, and PKC inhibitor GF109203X decreased the expression of phos-PKC, CaMKII, and NFκB in both A549 and A549/DDP lung cancer cells." (PMID 27895670, 2016). "In contrast, the Wnt5a-induced clonogenicity could be significantly inhibited by an addition of PKC inhibitor GF109203X in both A549 and A549/DDP cells (p < 0.01), implying that the Wnt5a was able to enhance the potency of lung cancer stem cells by activation of Wnt5a/PKC pathway." (PMID 27895670, 2016).
colon carcinoma (56 papers, 2009 to 2026). "Conversely, other research indicated that Wnt5a was consistently overexpressed in intestinal polyps and tumor samples, and elevated Wnt5a levels were associated with early recurrence or metastasis in colon cancer patients." (PMID 39200196, 2024). "We have previously shown by a univariate (Kaplan-Meier) overall survival analysis that patients with low WNT5A expression in their colon cancer tissue had a poor prognosis, with a high risk of progression and relapse." (PMID 37998393, 2023). "WNT5A was recently detected in colon CAFs and linked to colon cancer progression." (PMID 36683050, 2023). "Loss of WNT5A has been associated with a poor prognosis in a various cancers, including breast and colon cancer, neuroblastoma, and leukemia, indicating that WNT5A might play a tumor-suppressive role in these malignancies." (PMID 36476410, 2022). "For example, Wnt5a has been shown to decrease Lgr5/RSPO3 expression and β-catenin activity in vitro, and its expression has been associated with improved survival in colon cancer." (PMID 41008809, 2025). "A study demonstrated that treatment with genistein in SW1116 colon cancer cells reactivated the Wnt5a gene, which acts as an antagonist to the Wnt signaling pathway, frequently overactivated in colon cancer." (PMID 40239010, 2025). "To confirm that LGR5 and DCLK1 are both colon cancer stem cell markers and are related to WNT5A signaling, we studied colony and spheroid formation of colon cancer cells, assays used to demonstrate the presence of cancer stem cells." (PMID 37998393, 2023). "In the GSE44076 colon cancer cohort (N = 198), we next investigated a possible correlation between WNT5A mRNA and LGR5 mRNA expression." (PMID 37998393, 2023). "Since β-catenin signaling promotes colon cancer stemness, we explored how WNT5A expression is related to that of the cancer stem cell marker DCLK1." (PMID 37998393, 2023). "DCLK1 expression was negatively correlated with WNT5A expression in colon cancer cohorts and was experimentally reduced by WNT5A signaling." (PMID 37998393, 2023). "This has led to WNT3A being commonly used as an activator of β-catenin-dependent signaling and WNT5A often used as an activator of β-catenin-independent signaling in colon cancer cells." (PMID 37998393, 2023). "Expression of WNT5A (a tumor suppressor) negatively correlated with that of LGR5/RSPO3 (tumor promoters) in colon cancer cohorts." (PMID 37998393, 2023). "To fully evaluate such a possible inconsistency between the cancer stem cell markers LGR5 and DCLK1, we also investigated the expression and prognostic value of DCLK1 in the two colon cancer cohorts and how it correlated with WNT5A expression." (PMID 37998393, 2023). "The demonstration that RSPO3 is a driver of intestinal cancer, and the fact that LGR5 is a WNT/β-catenin signaling target urged us to explore a possible relationship between RSPO3 and LGR5 as well as WNT5A signaling in colon cancer tissues." (PMID 37998393, 2023). "The fact that both recombinant WNT5A signaling reduced colony and microspheroid formation indicates that WNT5A signaling can reduce the niche of colon cancer stem cells." (PMID 37998393, 2023). "Here, WNT5A promotes the formation of adhesion sites leading to directional migration, and this activity is reduced in Wnt5a knockdown colon cancer cells leading to reduced directional migration." (PMID 37722040, 2023). "In colon cancer, enhanced stromal Wnt5a expression promotes directional migration and invasion of cancer cells." (PMID 35210425, 2022). "WNT5A protein expression is reduced in Dukes B colon cancer tissue compared with normal tissue and is negatively correlated with the five-year survival rate, suggesting that the loss of WNT5A is a potential prognostic marker for colon cancer progression." (PMID 35595735, 2022). "Cecilia, Cheng, and Li argued that WNT5A is a protective factor that delays disease progression in colon cancer patients." (PMID 35155186, 2021).